ACE (angiotensin I converting enzyme)
Diseases named in the same sentence as ACE in open-access papers (continued):
Sharing a sentence is not in itself a finding about the gene and the disease.
COVID-19 (continued). "Curiously, people from blood group A are at higher risk of developing severe forms of COVID-19 and exhibit lower plasmatic ACE levels." (PMID 33519802, 2020). "Individuals with ACE gene polymorphisms are susceptible to the severe inflammation induced by COVID-19." (PMID 32708430, 2020). "There have been concerns regarding a potential harmful effect caused by ACE inhibitors and AR blockers in COVID-19 patients." (PMID 33127965, 2020). "Model predictions for ACE inhibitors are in agreement with clinical data, which indicate that treatment with ACE inhibitors is associated with better survival among COVID-19 patients." (PMID 33265982, 2020). "Corroborating this idea, recent studies have suggested ACE inhibitors are associated to poor prognosis in COVID-19 patients." (PMID 33519802, 2020). "The only and largest survey published so far assessing the association between comorbidities, use of ACE inhibitors/ARBs, and COVID-19 death included 4,480 patients from Denmark." (PMID 33195473, 2020). "On the contrary, a study on people from Europe, North Africa and the Middle East demonstrated an inverse correlation between prevalence and mortality due to COVID-19 and the ACE D allele frequency." (PMID 33585520, 2020). "Low activity of serum ACE at baseline was associated with the severity of COVID-19, and it increased with the remission of the disease." (PMID 33238910, 2020). "Medications: We found a higher risk of hospitalizations in COVID-19 patients who were on Angiotensin Converting Enzyme (ACE) inhibitors, or angiotensin II type-I receptor blockers (ARBs) on univariable analysis." (PMID 32780765, 2020). "It has also been reported that an increased level of plasma Ang II was strongly associated with lung injury severity in COVID-19 patients, which implied the activation of the ACE/AII/AT1R axis." (PMID 33238910, 2020). "Allelic and genotypic frequencies and Hardy Weinberg Equilibrium test for ACE I/D polymorphism rs1799752 in PE+ and PE− COVID-19 patients, and in the control population." (PMID 33585520, 2020). "The use of ACE inhibitors/ARBs in patients with COVID-19 or at risk of infection with the virus is currently a subject of intense debate, due to the evidence that SARS-CoV-2 uses the ACE2 receptor for entry into target cells." (PMID 33195473, 2020). "The use of ACE inhibitors has been suggested to increase the susceptibility to COVID-19 and worsen the COVID-19 outcome through an increase in the viral load." (PMID 33274196, 2020). "Inherited and environmental factors that alter the expression and function of RAAS components, such as ACE, could explain the risk of developing COVID-19 and its adverse outcomes." (PMID 40150043, 2025). "Common variants in the two ACE genes have been linked to symptoms observed in COVID-19." (PMID 40150043, 2025). "Differences in COVID-19 severity are thought to be due to the imbalance of RAAS/ACE mutations." (PMID 39591276, 2024). "The strong correlation between PTX3 serum levels, ACE I/D polymorphism, and the MBrixia score supports the hypothesis that endothelial injury and genetic factors are important in the pathogenesis of COVID-19." (PMID 39062191, 2024). "The ACE1 Deletion allele and D/D genotype, being associated with higher systemic ACE activity may constitute independent risk factors for COVID-19 severity." (PMID 38177248, 2024). "I allele were less frequent in patients with COVID-19 than controls suggesting that the ACE I allele may confer protection against COVID-19." (PMID 38177248, 2024). "Another potential explanation for the association between group A and severe COVID-19 is an increase in angiotensin-converting enzyme 1 (ACE-1) activity, which may predispose individuals to cardiovascular complications." (PMID 37927694, 2023). "Thus, a meta-analysis was performed to more accurately estimate the relationship of the ACE I/D polymorphism with the risk of COVID-19." (PMID 38058963, 2023).
COVID-19 (continued). "Thus, a meta-analysis of relevant articles was performed to more accurately estimate the relationship of ACE I/D polymorphism with the risk of COVID-19." (PMID 38058963, 2023). "Similarly, ACE-DD genotype was strongly associated with increased COVID-19 severity with OR 2.37, (95%) CI = (1.19–4.70), RR = 1.39 (1.09–1.77), p < 0.013." (PMID 36644496, 2023). "We also found a significant association between the ACE-2 rs908004 polymorphism and the total length of hospitalization among clinically severe COVID-19 patients (Patients with GG genotype had significantly more total length of hospital stay than other genotypes)." (PMID 37426824, 2023). "In light of the probable elevation the expression of ACE2 by these drugs, there has been growing suspicion that ACE inhibitors and Ang II receptor blockers may raise the risk of the onset and severity of COVID-19." (PMID 37796433, 2023). "ACE I/D polymorphism is correlated with the clinical severity of COVID-19 in different studies." (PMID 37432962, 2023). "Therefore, we aimed to investigate the association between ACE levels, ACE gene polymorphisms and the prognosis of COVID-19." (PMID 37432962, 2023). "The different clinical courses of COVID-19 among various populations may be associated, at least in part, with ACE gene polymorphisms." (PMID 37432962, 2023). "Furthermore, inhibition of ACE caused an increase in bradykinin levels and bronchoconstriction, which induced cough, a common symptom seen in COVID-19 patients." (PMID 37663382, 2023). "We also found a significant association between the ACE-1 rs4343 polymorphism and the total length of hospitalization among clinically severe COVID-19 patients (Patients with TT genotype had significantly more total length of hospital stay than other genotypes)." (PMID 37426824, 2023). "ACE’s importance in modulating the immune response can be seen in recent studies showing that lower serum ACE levels are associated with impaired host antiviral response to COVID-19 as well as studies showing increased risk of infection with ACE inhibitor use." (PMID 36969603, 2023). "The DD genotype of the rs1799752 ACE variant was associated with the IMV requirement in patients with COVID-19, and low serum ACE activity levels could be related to patients with severe disease." (PMID 37108839, 2023). "Moreover, Amar and colleagues in Pakistan found a probable correlation between the ACE I/D gene polymorphism and COVID-19 prevalence, fatalities, and recovery rate in a meta-regression analysis." (PMID 36644496, 2023). "For instance, some research suggested that angiotensin-converting enzyme (ACE) inhibitors have been associated with an increased risk of death from COVID-19, while others indicated an association between desirable clinical outcomes and the chronic use of ACE inhibitors." (PMID 36908454, 2023). "To conclude, the ACE D allele was clearly associated with an enhanced risk of COVID-19 severity." (PMID 38058963, 2023). "However, severe COVID-19 has been reported in other studies to be associated with a decrease in ACE activity and reduced Ang II/Ang I ratio, suggesting a defect in the classical RAS, associated with an increase in ACE2 activity." (PMID 37986086, 2023). "The ACE D allele was clearly related to an enhanced risk of COVID-19 severity." (PMID 38058963, 2023). "The deficiency or overexpression of ACE alters ANG I accumulation, which may promote virus infection 68 and may explain why ACE is a potential susceptibility gene for COVID-19." (PMID 35165525, 2022). "Altogether, it is suggested that the polymorphism of ACE gene may have a prominent role to play in determining the clinical outcomes or severity of COVID-19 cases." (PMID 36531237, 2022). "Considering the effects of this polymorphism on the activity and serum level of the ACE-1 enzyme, it might be postulated that carriers of specific genotypes of this variant may be more susceptible to COVID-19." (PMID 35305693, 2022).
COVID-19 (continued). "Besides ACE2 and Ang II, RAS can also be regulated by insertion/deletion (I/D) polymorphism of the ACE gene increasing the risk of severe forms of COVID-19." (PMID 36519165, 2022). "In addition, increased activity of ACE-1 in patients with blood group A predisposes to cardiovascular complications, responsible for severe COVID-19." (PMID 36013335, 2022). "A relationship between ACE polymorphisms and COVID-19 has also been reported." (PMID 35165525, 2022). "Nowadays, cardiovascular disease may be a double-edged factor, since it is a proven risk factor for COVID-19 severity, but some of the treatments used, such as ACE inhibitors, have also proved to be protective against severe infections from SARS-CoV-2." (PMID 35144239, 2022). "However, our results clearly revealed that rs4341 and rs4343 polymorphisms of the ACE gene are related to the risk of developing severe COVID-19 (ICU admission) in hypertense, dyslipidemic and diabetic patients." (PMID 34489863, 2021). "We posit that individuals with the ACE Alu DD genotype may be predisposed to complications of COVID-19 due to higher baseline ACE levels." (PMID 33390179, 2021). "The unique stem cell molecular signature, as well as the very low expression of angiotensin-converting enzyme 2 and the lower ACE/ACE2 ratio in stem cells of children/pregnant women compared to adults might be the cause of milder symptoms of COVID-19 in them." (PMID 34769218, 2021). "Interestingly, among patients with myocardial infarction (MI), the D-allele of ACE is associated with higher levels of IL-6, which has been associated with worse outcomes of COVID-19." (PMID 33390179, 2021). "Early in the pandemic there was speculation that certain medications, including statins, ACE inhibitors and ARBs, could confer an increased susceptibility to COVID-19 positivity and/or severity." (PMID 34264974, 2021). "The COVID-19 number and severity of cases in some populations have been associated with ACE gene and the frequency of I allele (insertion) or D allele (deletion) of 287-bp, drawing attention to the activity of this protein, which has a relationship with these genetic variants." (PMID 34384461, 2021). "The relationship between ACE polymorphisms and COVID-19 suggests that public health institutions should further strengthen the prevention for patients with the DD genotypes, and medical institutions need to carefully assess the progression of COVID-19 patients with the DD genotypes." (PMID 35095487, 2021). "In the current study, we investigated whether the ACE polymorphism is involved in the development of the COVID-19." (PMID 35095487, 2021). "Thus, COVID-19-associated decrease in ACE2 most likely results in disruption of the ACE/ACE2 balance in the kidney leading to sustained activation of ACE and Ang-II activities and kidney damage." (PMID 32901433, 2021). "In particular, ACE-2 polymorphism could be linked to multi-organ failures in COVID-19 patients and may cause mild to severe forms of the disease in certain groups, influencing the respective prevalence and mortality rate." (PMID 34399734, 2021). "An alternative hypothesis is that the differences in COVID-19 risk observed between ACE inhibitors and ARBs is due to residual confounding." (PMID 33722197, 2021). "Specifically, increased ACE2 expression in response to treatment with ACE inhibitors (ACEi) and Ang II receptor blockers (ARBs) might theoretically increase COVID-19 risk by increasing SARS-CoV-2 binding sites." (PMID 34017843, 2021). "In this group, the association between ACE polymorphism and COVID-19 was significant." (PMID 35095487, 2021). "In fact, several studies have suggested that variabilities in the genotype distribution of ACE polymorphisms could explain the variable prevalence and clinical outcomes of COVID-19 among different regions of the world." (PMID 34489863, 2021).
COVID-19 (continued). "In conclusion, this study suggested that the ACE deletion polymorphism may be associated with the susceptibility to COVID-19 in the Chinese population." (PMID 35095487, 2021). "Further research is also needed to assess whether the use of ACE inhibitors and ARBs is associated with COVID-19 hospitalisation and death and whether any such associations differ between drug classes." (PMID 33722197, 2021). "With this background, we performed a cohort study of vaccinated health care workers of a large university hospital in Milan, Italy to calculate the cumulative incidence (risk) of urticaria/angioedema after completion of BNT162b2 COVID-19 vaccination and the impact of ACE inhibitors on this risk." (PMID 34579248, 2021). "Taken together, the evidence suggests that a varied COVID-19 disease course in CF may in part be due to the association between ACE polymorphisms, effects on ACE2 downregulation, and resulting CF features, such as pulmonary inflammation." (PMID 34016096, 2021). "Indeed, an association of the DD genotype of the ACE I/D polymorphism with severe COVID-19 has been reported in hypertensive males." (PMID 34489863, 2021). "We investigated whether the insertion/deletion polymorphism in the ACE gene was associated with the susceptibility to COVID-19." (PMID 35095487, 2021). "Furthermore, COVID-19 prevalence correlated to allele frequency of angiotensin-converting enzyme (ACE) deletion (D) polymorphism within the European population." (PMID 32901433, 2021). "Interestingly, in rs4343 and rs4341 polymorphisms of the ACE gene, the presence of the G allele worsens COVID-19 outcome in diabetic patients, since patients admitted to the ICU had the GG genotype." (PMID 34834033, 2021). "Since some of these processes have been reported to be involved in the pathogenesis of COVID-19, the DD genotype could predispose to complications of COVID-19 due to higher baseline ACE levels and its consequences." (PMID 34489863, 2021). "Similarly, another study conducted in London, UK found the use of ACE inhibitors to be associated with reduced risk of COVID-19 severity and mortality." (PMID 33778087, 2021). "Moreover, genotype-specific cytokine storms and immune responses were found enriched in patients with the ACE deletion polymorphism, suggesting the contribution to the susceptibility to COVID-19." (PMID 35095487, 2021). "With respect to SARS-CoV-2, an intronic Alu within the ACE gene is hypothesized to be associated with COVID-19 susceptibility and morbidity." (PMID 33390179, 2021). "Thus, ethnic prevalence of ACE DD polymorphism can explain in part the severity of COVID-19 morbidity providing rationale for the use of ACE-I/ARBs to improve outcomes." (PMID 32901433, 2021). "There are also recent observations and discussions regarding the imbalance in RAAS caused by COVID-19 that might be protected by the use of ACE inhibitors in COVID-19 patients." (PMID 33118741, 2020). "In addition, a recent analysis of the prevalence of ACE (I/D) genotype in different countries showed that as the I/D allele frequency ratio increases, the COVID-19 recovery rate in each country also increases." (PMID 32984543, 2020). "A very recent report has indicated that the ACE I/D polymorphism may affect the spread and outcome of COVID-19." (PMID 33238910, 2020). "Serum ACE activity could be used as a marker to reflect the clinical condition of COVID-19 since low activity was associated with the severity of COVID-19 at baseline, and the activity increased with the remission of the disease." (PMID 33238910, 2020). "Also, the pathogenic role of angiotensin II in COVID-19 and the potential use of ACE/ARBS needs to be more clearly elucidated." (PMID 32403242, 2020). "Several hypotheses have been made on the association between COVID-19 progression and treatment with ACE inhibitors and ARBs." (PMID 32579597, 2020).
COVID-19 (continued). "The higher risk to develop worse outcomes in diabetic population infected with SARS-CoV-2 also can be associated with the reduced ACE2/ACE ratio in diabetic condition, which could be critical to several pathophysiological mechanisms of COVID-19." (PMID 33362575, 2020). "We also use publicly available data on genetic associations with COVID-19 susceptibility to investigate whether genetically predicted serum ACE levels are associated with risk of hospitalization due to COVID-19." (PMID 33391794, 2020). "Therefore, the relationship between the ACE I/D polymorphism, serum ACE activity and the outcome of patients with COVID-19 needs to be explored in the future." (PMID 33238910, 2020). "Recently, the hypothesis that ACE inhibitors could act as a potential risk factor for fatal COVID-19 by up-regulating ACE2 was proposed." (PMID 33195477, 2020). "Notably, ACE (I/D) polymorphisms have been implicated in COVID-19 and related CVT, and vary across racial groups." (PMID 33344513, 2020). "Many high-risk COVID-19 patients with comorbidities are on ACE inhibitors and angiotensin receptor blockers, and this has sparked debate about whether to continue these treatment regimes." (PMID 32369402, 2020). "Given that ACE2 facilitates viral invasion of human cells, there have been concerns that upregulation of ACE2, via use of ACE inhibitors and ARBs, may increase COVID-19 susceptibility and severity." (PMID 33414783, 2020). "Therefore, it is hypothesized that having the D allele for the ACE I/D polymorphism may worsen the clinical course of COVID-19 by decreasing ACE2 receptor levels." (PMID 40150043, 2025). "Second, our analysis did not adjust for the potential impact of treatments like corticosteroids, ACE inhibitors, statins, or vaccines on cardiovascular outcomes post-discharge, which may significantly confound the observed association between severe COVID-19 and increased cardiovascular risk." (PMID 39685724, 2024). "In addition, COVID-19 severity was associated with the ACE D/D genotype and with high CRP levels." (PMID 37238156, 2023). "Therefore, it is plausible that ACE I/D polymorphism may play a key role in COVID-19 patients who are susceptible to develop severe lung injury or ARDS." (PMID 36371754, 2023). "In addition, some studies found that the ACE I/D polymorphism could have the potential to predict the severity of COVID-19." (PMID 38058963, 2023). "Another review suggested that timely use of recombinant human erythropoietin (EPO), EPO analogs, acetylsalicylic acid, bioactive lipids, or FGF23 antagonists in genetically predisposed adults with the angiotensin-converting enzyme (ACE) D allele may induce detrimental effects in COVID-19 patients." (PMID 37637614, 2023). "Thus, we aimed to assess the association of the insertion/deletion ACE variant (rs1799752) and the serum ACE activity with the severity of COVID-19 and its impact in post-COVID-19 subjects and patients hospitalized with a respiratory disease different from COVID-19." (PMID 37108839, 2023). "This association could be due to the fact that drugs used to limit cardiovascular and cerebrovascular risk, such as ACE inhibitors and angiotensin II receptor blockers (ARBs), have numerous effects that could influence the susceptibility to or the severity of COVID-19." (PMID 36626821, 2023). "Dietary proteins may boost pulmonary function in SARS-COV-2 patients through inhibitory effects on the Angiotensin-converting enzyme (ACE) and reduce Angiotensin (ANG-II)." (PMID 37312883, 2023). "In severe COVID-19 patients, these may be linked to multiple factors, among them as the significant ones were the aged patients, reduced systemic oxygenation intake due to pneumonia, concomitantly increased cardiac demand, and use of ACE inhibitors." (PMID 35755851, 2022).